BDNF (brain derived neurotrophic factor)
Diseases named in the same sentence as BDNF in open-access papers (continued):
Sharing a sentence is not in itself a finding about the gene and the disease.
Obesity (continued). "In a mouse model of obesity and diabetes a molecular autoregulatory system was developed to target the BDNF (brain-derived neurotrophic factor) gene which is involved in the regulation of energy balance in the hypothalamus." (PMID 21506921, 2011). "Thus, we demonstrate that the currently known major common variants related to obesity overlap to a substantial degree between children and adults confirming previous observations for FTO, MC4R, TMEM18, NEGR1 and extending this observation to SEC16B, BDNF and BCDIN3D;." (PMID 20421936, 2010). "We have found associations (with p values less than 0.05) for SGA with the diabetes related SNP in KCNJ11 and the obesity related SNPs in FTO, PFKP, PTER, SEC16B and BDNF." (PMID 20712903, 2010). "By contrast, the two studies that enrolled children with overweight or obesity found no significant changes in BDNF levels." (PMID 40724649, 2025). "Lastly, an effect of the interaction of BDNF SNP rs6265 with PA was observed in increased WC but not in other obesity-related variables." (PMID 39283705, 2025). "Acute and sustained physical activity increases serum BDNF levels in adults as well as in youth with and without obesity." (PMID 38997217, 2024). "Meanwhile, the previous study showed that food restriction initiated at 6 weeks of age, a period at which obesity in BDNF heterozygous mice is not yet apparent, induced normalization of body weight, and serum glucose and insulin levels." (PMID 38672461, 2024). "Elevated anti-inflammatory cytokines (IL-4 and IL-10) and neurotrophic factors (BDNF, IGF-1) in silymarin-treated mice suggest that silymarin may offer neuroprotective benefits by mitigating obesity-related neuroinflammation." (PMID 39624169, 2024). "Genes in the leptin–melanocortin pathway, such as leptin (LEP), leptin receptor (LEPR), melanocortin-4 receptor (MC4R), adenylyl cyclase 3 (ADCY3), and brain-derived neurotrophic factor (BDNF) genes, are established contributors to obesity and insulin resistance." (PMID 38674857, 2024). "Even though perturbing BDNF signaling in the VMH does not result in severe obesity, as observed in mice depleted of BDNF or TrkB in the PVN, it significantly compromises feeding and weight control, with concomitant alterations in glucose homeostasis." (PMID 38672441, 2024). "BDNF is also a regulator of mitochondrial fission and mitophagy by promoting PINK1 and Parkin attachment to the mitochondria of myofibers, which is an essential mechanism to protect against obesity-impaired mitochondria turnover." (PMID 39531828, 2024). "Ablation of Sh2b1 in PVHSH2B1 neurons induces BDNF resistance in the PVH, contributing to obesity." (PMID 38885417, 2024). "The brain-derived neurotrophic factor (BDNF)/tyrosine receptor kinase-B (TRKB) pathway has been considered as potentially relevant as it is related to respiratory control, the lung-brain axis, and the development of obesity in animal models." (PMID 39595809, 2024). "BDNF expression in the VMH can be stimulated by signals of nutrient availability or inhibited by nutrient restriction leading to excessive feeding (hyperphagia) and obesity in mice (see for review)." (PMID 39194496, 2024). "Nonetheless, excessive leptin secretion did not suppress appetite and induced obesity in BDNF heterozygous mice." (PMID 38672461, 2024). "At present, BDNF, NGF, and pro-NGF play a crucial role in the pathogenesis of a wide spectrum of neuronal and non-neuronal disorders, such as Alzheimer’s and other neurodegenerative disorders, including obesity and related CMD." (PMID 39065809, 2024). "However, NTFs also play an increasingly emerging role in chronic disease pathways such as obesity, such that NGF and BDNF have been described among a family of metatrophic factors involved in glucose homeostasis." (PMID 38540381, 2024). "Our findings in Thai children did not support the concept that BDNF inadequacy induces a metabotropic impairment leading to obesity." (PMID 37007871, 2023).
Obesity (continued). "Our results seem to align with previous studies that have reported a negative correlation between serum BDNF levels, obesity markers, and inflammation." (PMID 37139092, 2023). "Although Shiikuwasha has an anti-obesity effect and other therapeutic properties, no study has investigated its effect with respect to upregulating BDNF level and acting as an antidepressant." (PMID 38082356, 2023). "The decline in performance could be due to the negative impact of obesity on the integrity of the Hc and other brain regions, such as the Cx, as well as the changes in synaptic plasticity and dendritic spine density associated with neuroinflammation and BDNF dysregulation." (PMID 37139092, 2023). "In our study, obesity had minor, or no impact on serum BDNF concentrations in males, as opposed to females." (PMID 37548699, 2023). "Therefore, this trial mainly aimed to examine the effect of thylakoid intervention on oxidative level, LPS as marker of gut permeability, and BDNF and S100B levels as neurotrophic factors in PCOS women with obesity who were on a low-calorie diet." (PMID 37968684, 2023). "For example, elevated levels of IL-6, IL-1β, and TNF-α mRNAs and reduced expression of brain-derived neurotrophic factor (BDNF) were found in the hippocampus of mice lacking leptin receptor (db/db mice), a genetic model of obesity." (PMID 37373230, 2023). "As in the case of decorin above, there are, unfortunately, no studies relating obesity phenotypes to BDNF action." (PMID 38136166, 2023). "So, it is not surprising that there is a lower circulating BDNF among diabetic patients and individuals with obesity or metabolic disorder compared with healthy people." (PMID 37072879, 2023). "A recent study using mice with selective knockdown of BDNF production from either promoter I, II, IV, or VI showed that disruption of BDNF from promoter I or II, but not IV or VI, induces hyperphagic obesity." (PMID 35242012, 2022). "In addition, the correlation of BDNF and NGF with salivary insulin, blood pressure, and obesity measures were evaluated." (PMID 35626286, 2022). "However, studies regarding DNA methylation alteration in key CpGs of the regulatory BDNF region in T2DM and obesity are still scarce and warrant further investigation." (PMID 35225959, 2022). "Hence, the aim of this clinical trial is to investigate the effect of TRF on anthropometric indices, stress level, eating behavior, and serum levels of BDNF and LBP in women with overweight/obesity and food addiction." (PMID 35689257, 2022). "We already explained in the previous section, and based on literature findings, that an increase in miR-204 in obesity could lead to downregulation of SIRT1 and BDNF and, therefore, to a decrease in the SNA." (PMID 35155042, 2022). "BDNF concentrations were comparable in children with obesity, both with and without OSA, indicating that BDNF levels are not affected by OSA." (PMID 35127775, 2021). "BDNF levels were comparable in children with obesity and OSA and children with obesity but without OSA (26.75 vs. 27.87 ng/ml, p = 0.6)." (PMID 35127775, 2021). "Gender and age had no regulatory effect on the relationship between overweight/obesity, BDNF, 5-HT, and EC." (PMID 33916706, 2021). "It has to be emphasized that in the present study, no group difference between patients suffering from obesity and normal-weight participants with respect to food craving, as well as BDNF levels were revealed." (PMID 33367955, 2021). "Recent studies have shown that diet induced obesity in mice results in impaired hippocampal memory, but there is no significant change in BDNF, which is consistent with our results." (PMID 34530850, 2021). "With this well-established role of BDNF, it can be argued that the absence of BDNF lessen SST effect in obesity independent of inhibitory action of SST in the regulation of key hormones involved in obesity." (PMID 32272767, 2020).
Obesity (continued). "Collectively, maternal HFD/obesity decreased adiponectin, pAKT, SIRT1, and BDNF in male rat fetal brain and maternal resveratrol treatment could restore adiponectin, pAKT, and BDNF." (PMID 32408716, 2020). "At baseline, the BDNF level was similar between the preoperative DM (n = 30) (17.1 ± 7.7 ng/ml) and non-DM (n = 48) (17.0 ± 6.9 ng/ml) patients with obesity, but FGF21 was significantly higher in the DM patients (201.5 ± 204.3 versus 107.6 ± 63.8 pg/ml)." (PMID 32210348, 2020). "Collectively, maternal HFD/obesity decreased adiponectin, pAKT, SIRT1, and BDNF in rat placenta." (PMID 32408716, 2020). "There are several possible mechanistic explanations by which BDNF and SST may affect obesity and energy homeostasis." (PMID 32272767, 2020). "It indicates that BDNF can modulate in part on the DMH to control bodyweight, suggesting that activation of DMH by the TrkB neurons could be a powerful way to treat obesity." (PMID 32982666, 2020). "Hippocampal neurogenesis is suppressed by the increase of oxidative stress and the decrease of a brain-derived neurotrophic factor (BDNF), which is involved in the enhanced hippocampal neurogenesis under a high fat diet (HFD) related to obesity and Type 2 diabetes." (PMID 32438638, 2020). "Further studies are necessary to determine the link between glucose metabolism, peripheral hormones (such as GLP-1, leptin and ghrelin), BDNF and hippocampal 5-HTT signaling and its biological relevance with regard to preventive and therapeutic consequences in individuals with obesity." (PMID 33288788, 2020). "Furthermore, genetic variants thought to be implicated in BD such as BDNF, MTHFR, GNAS, and CACNA1C/D, have been hypothesized to overlap between BD and CVD, conferring risk of mood disorders in addition to risk of hypertension, type 2 diabetes, obesity, and dyslipidemia." (PMID 30761021, 2019). "BDNF levels are activity-dependent, which means that the expression of BDNF changes under positive (e.g., physical activity, cognitive enhancement) and negative (e.g., obesity, sedentarism) behavioral and environmental stimuli." (PMID 30117106, 2019). "Previous studies have demonstrated that high-fat feeding and obesity increase the production of BDNF and phospho-CREB in the striatum contributing to negative emotional states and depressive-like symptoms." (PMID 31933694, 2019). "Although direct evidence for brain-derived neurotrophic factor (BDNF) in the link between obesity and mood disorders has not been established, its involvement in both conditions makes BDNF an important candidate." (PMID 31118969, 2019). "In humans, WAGR patients with BDNF haploinsufficiency had reduced cognitive functioning, lower adaptive behaviour and higher levels of obesity, compared to those without a BDNF deletion." (PMID 30242502, 2019). "In fact, adults with obesity and adults with T2D have significantly lower circulating BDNF compared to lean, nondiabetic adults, possibly owing to hyperglycemia-induced reductions in plasma BDNF." (PMID 30363954, 2018). "To date, a number of studies have shown that myokines, such as interleukin-6 (IL-6), interleukin-15 (IL-15) and brain-derived neurotrophic factor(BDNF), may be potential regulators of many physiological states and metabolic diseases, such as obesity and IR." (PMID 28702069, 2017). "Moreover, recent reports of obesity-related loci enriched in brain-expressed genes such as FTO, MC4R, GNPDA2, and BDNF point to a neuronal influence on body weight regulation in adults." (PMID 29212175, 2017). "The mean fasting BDNF concentration in the obesity group was not significantly different from that in the control group (40.4 7.8 vs. 43.0 ± 6.1 ng/mL, P = 0.171)." (PMID 27787389, 2016). "The cut-off value of 6% weight reduction yielded a sensitivity of 95% and specificity of 53% for a negative BDNF AUC index in the subjects with obesity after the study." (PMID 27787389, 2016).
Obesity (continued). "The cut-off value of 6% reduction in weight was demonstrated to predict a negative BDNF AUC index in men with obesity." (PMID 27787389, 2016). "Since BDNF is only absent in the brain, the resulting obesity can be attributed to the lack of BDNF function therein." (PMID 25825681, 2015). "Although the mechanism of most genetic loci predispose individuals to obesity is not clear so far, evidence indicated that they were involved in energy uptake (FTO, MC4R, PCSK1, and BDNF) and adipocyte differentiation (FTO, TMEM18, BDNF, MTCH2 and NEGR1)." (PMID 24626232, 2014). "BDNF is thought to act as an anorectic factor: like PACAP, infusions of BDNF into the lateral ventricles lead to a reduction in food intake and a number of BDNF mutant mouse models have demonstrated obesity phenotypes." (PMID 24400163, 2013). "This evidence shows a dominant role of hyperphagia in the development of obesity when BDNF signaling is impaired; however, it is not sufficient to rule out a role for BDNF in the regulation of energy expenditure." (PMID 23519010, 2013). "The same workers reported that plasma levels of BDNF were decreased in humans with T2DM, independently of obesity, suggesting that BDNF may regulate obesity and insulin resistance via different mechanisms." (PMID 23431394, 2013). "Leaving the hypothesis-free approach and focussing on known GWAS-based candidate markers, we were able to substantiate another four loci (NEGR1, SEC16B, BDNF and BCDIN3D) of the 16 obesity loci previously detected in GWAS." (PMID 20421936, 2010). "Interestingly, studies on healthy children have consistently reported positive BDNF responses, while those focusing on children with obesity or overweight have shown no significant changes." (PMID 40724649, 2025). "Similarly, Seok-Min and Chol-Hyoung reported non-significant increases in BDNF after 12 weeks of combined aerobic and strength training in adolescents with obesity." (PMID 40863762, 2025). "The BDNF rs6265 non-risk allele was positively associated with BMI, waist circumference, and body fat mass; heterozygotes and minor alleles were positively associated and SMI was inversely associated with obesity." (PMID 40002356, 2025). "Considering that CX3CL1 in the peritoneal cavity signals to the hippocampus through the modulation of peritoneal immune cells, it could be speculated that the increased adipose CX3CL1 in obesity does not promote the hippocampus BDNF." (PMID 40724847, 2025). "Additionally, the obesity observed in the 11p13-14 contiguous gene deletion WAGRO syndrome (Wilms tumor, aniridia, genitourinary abnormalities, mental retardation, obesity) has been ascribed to BDNF haploinsufficiency." (PMID 38019584, 2024). "The expression of BDNF in both neuronal and non-neuronal cells is influenced by various stimuli, including prenatal developmental factors and postnatal conditions such as estrogens, dietary habits, and lifestyle factors like obesity, blood pressure, and aging." (PMID 39655343, 2024). "However, the relationship between BDNF and obesity in children is not clear, and the reported findings are inconclusive." (PMID 37638319, 2023). "However, another study found no increase in resting serum BDNF levels after six months of aerobic training, resistance training, or their combination in adolescents with overweight and obesity." (PMID 37763162, 2023). "The many hypotheses and contradictory results do not currently allow a clear definition of the role of BDNF in the development of metabolic disorders and obesity." (PMID 38136166, 2023). "Brain-derived neurotrophic factor (BDNF), secreted protein acidic and rich in cysteine (SPARC), fibroblast growth factor 21 (FGF-21), growth differentiation factor 15 (GDF-15) are examples of such cytokines which have therapeutic potential in obesity and metabolic diseases." (PMID 37436597, 2023).
Obesity (continued). "Furthermore, most human studies have focused on the role of BDNF in obesity among diabetics and those with mental disorders but not on obesity among healthy individuals." (PMID 36676721, 2022). "In contrast, the relationship between peripheral BDNF and obesity is not well-defined." (PMID 35911513, 2022). "More importantly, the LI protocol improved insulin sensitivity, reduced fasting insulinemia, improve the level of the obesity-related adiponectin, decreased the level of the pro-inflammatory marker TNF-alpha and Il-6, and positively modulated the levels of exercise-induced myokines, irisin and BDNF." (PMID 35120179, 2022). "Among the available phenotypes, obesity was chosen because it has been subjected to a number of high quality and well-powered GWAS that have identified more than 100 loci, many that have been consistently replicated across studies (e.g. FTO, BDNF, MC4R, TMEM18, SEC16B)." (PMID 33947323, 2021). "The main findings in this study revealed that the juveniles with obesity and T2DM exhibited reduced levels of resting neurotrophic factors, such as BDNF and its receptor (TrkB) at baseline, but after the 12 weeks of endurance exercise, there was a significant increase in the BDNF levels." (PMID 33672171, 2021). "No studies have investigated the effect of OSA and obesity on BDNF in a pediatric population." (PMID 35127775, 2021). "Likewise, obesity can have negative effects on the expression of neurotrophic factors (NTFs), such as the brain-derived neurotrophic factor (BDNF) and vascular endothelial growth factor (VEGF), which are involved in neurogenesis." (PMID 32244926, 2020). "Recent studies suggest that obesity and high‐fat diet (HFD) feeding with peripheral inflammation lead to deterioration in cognitive function and neurogenesis, probably via both, the dysregulation of brain‐derived neurotrophic factor (BDNF) and the increase in brain inflammation." (PMID 32681810, 2020). "Most importantly, how SST might be involved in the regulation of BDNF mediated function in obesity is not known yet." (PMID 32272767, 2020). "Intracerebroventricular infusion of recombinant human BDNF decreased food intake in rats, whereas genetic deletion of Bdnf gene in the VMH or the paraventricular nucleus of hypothalamus (PVH), another brain area related to energy intake, led to hyperphagia and obesity in mice." (PMID 30555354, 2018). "A sedentary life style, overweight, obesity and lack of exercise are related to reduced BDNF signaling and increased activity of the sympathetic nervous system, decreased activity of the parasympathetic outflow, increased heart rate, blood pressure, elevated inflammation, and reduced gut motility." (PMID 30542302, 2018). "Neither serum nor plasma BDNF correlate with body weight or obesity." (PMID 27352030, 2016). "Furthermore, transgenic mice lacking specific proteins expressed in the VMH including leptin receptor, steroidogenic factor 1 (SF-1), melanocortin-4 receptor (MC4R), and brain-derived neurotrophic factor (BDNF), exhibits obesity, hyperphagia, and low locomotor activity similar to AC3−/− mice." (PMID 19750222, 2009). "Thus, BDNF may be used as a biomarker of muscle strength rather than muscle mass and decreased BDNF levels in people with obesity and T2D may promote or reflect sarcopenic obesity." (PMID 40171198, 2025). "Hence, inadequate activation of Nrf2 by suppressed Sirt1 and BDNF levels, as observed in the present study, may lead to insufficient expression of antioxidants and thus, to low‐level chronic neuroinflammation when HFD/obesity persists." (PMID 39230054, 2024). "Finally, we did not analyze the entire BDNF gene in relation to obesity." (PMID 37007871, 2023). "However, it remains unknown whether BDNF-expressing PVH (PVHBDNF) neurons are actively involved in the control of energy balance and whether activation of PVHBDNF neurons presents an opportunity for obesity treatment." (PMID 35338053, 2022).